FDXR (ferredoxin reductase)
Diseases named in the same sentence as FDXR in open-access papers (continued):
Sharing a sentence is not in itself a finding about the gene and the disease.
radiation sickness (1 paper, 2022). "Up-regulation of FDXR and DDB2 GE indicates risk of mild acute radiation sickness, whereas an up-regulation of FDXR and DDB2 combined with a down-regulation of WNT3 and POU2AF1 predicts severe ARS10,11." (PMID 35680903, 2022). "Specific radiation-sensitive genes (such as FDXR, DDB2, WNT3, POU2AF1) have become well established for biodosimetry purposes and acute radiation sickness (ARS)-prediction." (PMID 35680903, 2022).
retinal degeneration (1 paper, 2025). Degeneration of the retina. "Complete pale optic disc, silver wiring of retinal vessels and salt-and-pepper retinal degeneration, mostly in the mid-peripheral area, were observed in our in-house patients carrying FDXR mutations." (PMID 39423307, 2025).
steatosis (1 paper, 2025). Increased lipid within the cytoplasm of cells. "Our findings demonstrate that FDXR deficiency impairs mitochondrial oxidation, disrupts iron homeostasis, and exacerbates oxidative stress, thereby promoting steatosis." (PMID 40909793, 2025). "Conversely, hepatic overexpression of FDXR enhanced mitochondrial oxidative capacity and alleviates steatosis, providing insight into its potential as a therapeutic target for MASLD." (PMID 40909793, 2025). "Mechanistically, FDXR deficiency disrupted iron-sulfur cluster assembly and reduced mitochondrial proteins such as succinate dehydrogenase complex iron-sulfur subunit B (SDHB), leading to mitochondrial dysfunction and steatosis." (PMID 40909793, 2025). "Furthermore, hepatic overexpression of FDXR restored mitochondrial function, enhanced oxidative capacity, and ameliorated steatosis." (PMID 40909793, 2025). "In contrast, hepatic overexpression of FDXR restored mitochondrial oxidation, increased TCA cycle activity, and alleviated steatosis in a mouse model, suggesting that therapeutic strategies aimed at enhancing FDXR activity could have significant potential in addressing MASLD." (PMID 40909793, 2025). "In contrast, FDXR overexpression enhanced TCA cycle flux in the liver and alleviates steatosis." (PMID 40909793, 2025).
tumor (21 papers, 2014 to 2025). "In vivo, elesclomol-Cu and CP-31398 combination therapy significantly reduced tumor growth and Ki67 expression whilst upregulating FDXR levels." (PMID 40630211, 2025). "HNF4A interacts with proteins that are little characterised such as ACSS3, BDH1 and FDXR, and highlights the need for further functional investigations of these proteins in tumour pathogenesis." (PMID 24728830, 2014). "Moreover, FDXR was also found to interact with the Fhit protein, a tumor suppressor, to modulate apoptosis, potentially through the regulation of ROS levels." (PMID 41511346, 2025). "Further, overexpression of FDXR increases the sensitivity of tumor cells to apoptosis." (PMID 35806169, 2022). "In addition, gene co-expression analysis using TCGA OV tumor dataset with GEPIA2 indicated that the expression level of ERβ positively correlated with FDXR and CDKN1A." (PMID 35806169, 2022). "Thus, our data indicate that FDXR regulates tumor cell growth through CPT1A." (PMID 37207154, 2023). "Some studies have found that FDXR with FDX2 deletion regulates P73 tumor suppressor via IRP2 to modulate aging and tumor suppression." (PMID 38898987, 2024). "Transcriptomic analysis showed LY500307 increased expression of tumor suppressor genes such as CDKN1A and FDXR." (PMID 35806169, 2022). "Recent studies have shown that ferredoxin reductase regulates the expression of TP73 by binding to iron-binding proteins, thereby regulating aging and tumor inhibition." (PMID 34257653, 2021).
tumor (continued). "The present study indicated a significant upregulation of ferredoxin reductase (FDXR) and a significant down-regulation of methionine sulfoxide reductase (MSR) genes following TPT treatment in both MCF-7 and ZR-75-1 tumor cells." (PMID 32765594, 2020).
cancer (13 papers, 2011 to 2025). A tumor composed of atypical neoplastic, often pleomorphic cells that invade other tissues. "A previous study demonstrated that impaired CPT1A expression is associated with disrupted fatty acid oxidation in FDXR-depleted cancer cells." (PMID 40909793, 2025). "Conversely, cancer cells deficient of FHIT expression cannot protect FDXR from proteasomal degradation and escape apoptosis as they are less sensitive to oxidative stress." (PMID 24901304, 2014). "A deeper understanding of these mechanisms may reveal new therapeutic opportunities for treating diseases associated with FDXR dysfunction, including various mitochondrial disorders and cancers." (PMID 41511346, 2025). "Further analysis of a larger cohort of patients and healthy donors would be required to identify a role of FDXR-202 and/or FDXR-205 as potential cancer biomarkers." (PMID 33113898, 2020). "As a result, increased FDXR sensitizes cancer cells to oxidative stress-induced apoptosis." (PMID 35889404, 2022). "For example, human cytochrome c1, whose gene is regulated by E2F, participates in an electron transport chain and the mitochondria pathway of apoptosis whereas a similar set of electron transport-related genes (COX8, CYB5-M, CYP51A1, FDXR and SUCLG1) were found to be E2F4-bound in cancer cell lines." (PMID 22076139, 2011).
mitochondrial disease (6 papers, 2021 to 2025). "Loss-of-function variants in the ferredoxin reductase (FDXR) gene result in a primary mitochondrial disease in humans, involving abnormal mitochondrial iron accumulation." (PMID 41436440, 2025). "Patients with germline FDXR mutations are prone to mitochondrial disease, with some dying at a very young age." (PMID 41511346, 2025). "Ferredoxin reductase deficiency has been reported to cause mitochondrial disease with broad spectrum of phenotypic features dominated by nervous system involvement." (PMID 33938912, 2021). "We speculated that mutations essential for electron transfer likely disrupt FDXR’s reductase function, contributing to mitochondrial disease." (PMID 41511346, 2025). "Furthermore, we will demonstrate that the NRF2/SLC7A11 antioxidant response pathway, which is critical in inhibiting ferroptosis in several biological contexts, is downregulated in FDXR-related mitochondrial disease." (PMID 41436440, 2025). "Not surprisingly, loss of FDXR function causes severe mitochondrial diseases in humans." (PMID 39669623, 2024).
peripheral neuropathies (1 paper, 2024). "Review of the literature revealed 77 patients with 59 biallelic FDXR mutations presenting with visual and hearing defects and a broad range of central and peripheral neuropathies." (PMID 38885337, 2024).
FDXR also shares sentences with these, for which no sentence is quoted: peripheral sensory neuropathies (3 papers); Ataxia (2); auditory neuropathy (2); infection (2); malaria (2); neurologic disorders (2); sensorial neuropathies (2); Skin ulcer (2); alopecia (1); autoimmune disease (1); autosomal recessive optic atrophy (1); calcinosis (1); colon cancer (1); COVID-19 (1); cyst (1); developmental delay (1); dyslipidaemia (1); energy metabolism disorders (1); genetic disorders (1); Genetic obesity (1); glioma (1); hearing loss (1); hematological disorders (1); hyperlipidaemia (1); Hypertension (1); interstitial lung disease (1); melanoma (1); mesothelioma (1); metastatic colorectal cancer (1); multiple mitochondrial dysfunctions syndrome 9b (1).
A further 6 diseases each share a sentence with FDXR in 1 paper.